IL6 (interleukin 6)
Diseases named in the same sentence as IL6 in open-access papers (continued):
Sharing a sentence is not in itself a finding about the gene and the disease.
hepatocellular carcinoma (continued). "Further researches on molecular mechanisms showed that activated STAT3 pathway by IL-6 upregulated CD47 expression in hepatocellular carcinoma cell lines, and the IL-6-STAT3 axis blockage reduced cancer cells' antiphagocytic ability via downregulation of CD47 expression." (PMID 35281519, 2022). "In hepatocellular carcinoma, one of the synthetic analogs of chrysin named 8-bromo-7-methoxychrysin suppressed the activation of hepatic stellate cells to CAFs and decreased the level of stemness of cancer cells by modifying IL-6 and HGF signaling." (PMID 35327514, 2022). "However, another study demonstrated that IL-6 controls PD-L1 expression through post-translational modification by inducing PD-L1 glycosylation necessary for its stability in hepatocellular carcinoma." (PMID 35326493, 2022). "In addition, ICT downregulates the IL-6/JAK2/STAT3 pathway activity to inhibit hepatocellular carcinoma-initiating cells (HCICs) and effectively reduces the expression of HCIC markers, such as EpCAM, CD133, and CD24, in a dose-dependent manner." (PMID 35600861, 2022). "The expression of HCV polymerase NS5B in mouse liver contributes to liver inflammation by the significant induction of IL-6, which may contribute to chronic liver inflammation and its progress to hepatocellular carcinoma in patients with chronic HCV." (PMID 36016430, 2022). "To investigate whether TNF-α promotes Hepa1-6 cell proliferation in an inflammatory state, we measured the levels of the inflammatory hepatocellular carcinoma-related cytokine IL-6 in Hepa1-6 cells treated with 50 ng/ml TNF-α." (PMID 35676936, 2022). "IL-6 promoter hypomethylation is present in hepatocellular carcinoma, and it may be used as a noninvasive biomarker to detect early liver cancer." (PMID 35359408, 2022). "Similarly, high levels of IL-6 in hepatocellular carcinoma correlate with poor survival prognosis and recurrence." (PMID 36294509, 2022). "Furthermore, secretion of CXCL12/SDF1 by hepatic carcinoma-derived CAFs attracts monocytes into the tumor stroma and engages their differentiation into MDSCs in an IL-6- and STAT3-dependent manner." (PMID 36338519, 2022). "Current research indicates that HBX can promote IL-6 expression in hepatoma cells." (PMID 35251017, 2022). "It has been reported that IL-6 released by drug-resistant hepatocellular cancer promotes the expansion and activity of MDSCs, and the interactions between IL-6 and MDSCs promote the chemoresistance of hepatocellular cancer." (PMID 35154134, 2022). "Besides, diethylnitrosamine (DEN) administration induced higher serum interleukin-6 (IL-6) production in males than it did in females in DEN-induced hepatocellular carcinoma model." (PMID 35309296, 2022). "Moreover, IL-6-activated STAT3 condensates have also been observed in the cytoplasm of hepatoma cells; these are disrupted by 1,6-hexanediol and hypotonic stress." (PMID 35406728, 2022). "Also, increased amounts of inflammatory mediators such as TNF-α, C-reactive protein, and IL-6 have been found in the sera of hepatocellular carcinoma patients." (PMID 36430792, 2022). "The cytokines released by macrophages may promo-te tumor progression, such as IL-6 in pancreatic cancer and hepatoma." (PMID 36362054, 2022). "in 2008 also showed that IL-6 could induce a growth arrest in rat hepatoma cells in a STAT-3-dependent manner through regulation of CDK activity." (PMID 35127527, 2021). "However, progranulin function in hepatocellular carcinoma is mediated through the mTOR pathway, and in cholangiocarcinoma, it involves the IL-6/progranulin/Akt axis." (PMID 34681875, 2021). "In addition, we demonstrated that downregulation of TNFAIP1 induced the expression of pro-inflammatory cytokines IL-6 and IL-8 in TNFα-stimulated hepatocellular carcinoma cells through the activation of p38/JNK MAPK pathway via blocking RhoB degradation." (PMID 33553178, 2021).
hepatocellular carcinoma (continued). "For instance, TAMs could enhance the proliferation of CSCs derived from hepatocellular carcinoma through IL‐6‐induced STAT3 activation." (PMID 33463006, 2021). "In the serum of patients with hepatocellular carcinoma and supernatants of peripheral monocytes cocultured with Huh7 cells, the levels of cytokines (IL-4, IL-6, and IL-10) could be upregulated, while the level of IFN-γ could be downregulated." (PMID 33435880, 2021). "A previous mechanistic study reported that IL-6 derived from TAMs could increase the expression of CD47 in hepatoma cells via activation of the STAT3 pathway." (PMID 34573091, 2021). "However, sesamin has the ability to suppress the STAT3 signaling pathway (IL6/JAK/STAT3) in human hepatocellular carcinoma cell line HepG2." (PMID 33578642, 2021). "Likewise, Morusin induced apoptosis and inhibited angiogenesis in hepatocellular carcinoma cells by inhibiting the IL6/STAT3 signaling pathway." (PMID 34638959, 2021). "In order to determine whether this effect was restricted to Hep3B cells or could be also seen in other hepatoma cell lines, we performed similar experiments with HepG2 cells, which we have previously used to analyze IL-6 signaling." (PMID 34281231, 2021). "In addition, IL6 can promote the expansion of CSCs in hepatocellular carcinoma and metastatic breast cancer." (PMID 33576874, 2021). "Furthermore, the upregulation of this gene, as well as CCL2, IL6, and LOXL2, has been implicated as part of the effects of cancer-associated fibroblasts in promoting progression of hepatocellular carcinoma cells." (PMID 32154227, 2020). "Dasatinib, an indirect STAT3 inhibitor against SRC/ABL, significantly facilitated anti-CTLA-4 immunotherapy in head and neck squamous cell carcinoma, while the combined blockade of IL-6 and PD-L1 remarkably inhibited the growth of pancreatic ductal adenocarcinoma and hepatocellular carcinoma (HCC)." (PMID 32972405, 2020). "For instance, through secretion of IL-6, CAFs derived from human hepatocellular carcinoma are able to upregulate the activation of the STAT3 signalling pathway in DCs, which in turn, induces a regulatory DC phenotype which is unable to prime and activate T cells." (PMID 32967079, 2020). "Furthermore, we also found that SMILE inhibited IL-6-mediated hepcidin secretion in both human and mouse hepatoma cells." (PMID 32545266, 2020). "In hepatoma cell line, palmitate increased IL-6 and TNF-α expressions and pJNK level." (PMID 31913329, 2020). "Our results indicated that HO-1 is the antitumor gene induced by IL-6 through the IL-6/JAK/STAT3 pathways; moreover, a feedback circuit may exist between IL-6 and HO-1 in hepatoma cells." (PMID 32204510, 2020). "Since a recent study indicated that IL-6 drives ROS reduction by increasing Nrf 2, a transcription activator of the HO-1 gene, expression in human islet β-cells, further investigations into the role of IL-6–HO-1 crosstalk in hepatoma cells, in terms of ROS synthesis, are warranted." (PMID 32204510, 2020). "Our results showed that the production of IL-4, IL-6, and IL-10 in H22 hepatoma bearing mice treated with DCs stimulated by ESPs was significantly reduced, while the expression of IFN-γ was markedly increased, which was the opposite to the cytokine expression in the ESP group." (PMID 32692308, 2020). "We continued to investigate the gene regulation of HO-1 by IL-6 in hepatoma cells." (PMID 32204510, 2020). "These compounds decreased the gene expression of tumor necrosis factor-alpha (TNF-α), interleukin-6 (IL-6) and interleukin-1beta (IL-1β) in lipopolysaccharide (LPS) induced inflammation in a hepatocellular carcinoma cell line (HepG2) in a dose-dependent manner." (PMID 31484451, 2019). "Furthermore, we detected lower levels of interleukin (IL)-35 in both types of transplanted hepatomas and higher level of IL-6 in orthotopically transplanted hepatomas following sFGL2 depletion." (PMID 31409352, 2019).
hepatocellular carcinoma (continued). "In addition, we also tested other inflammatory factors, such as IL-6 and TNFα, for their induction of PD-L1 expression on hepatoma cells." (PMID 31727135, 2019). "The inflammatory cytokine interleukin-6 (IL-6) is critical for the expression of octamer-binding transcription factor 4 (OCT4), which is highly associated with early tumor recurrence and poor prognosis of hepatocellular carcinomas (HCC)." (PMID 31771617, 2019). "There is recent evidence that LRG1 is induced by IL-6 and synergistically up-regulated with either IL-1β or tumor necrosis factor-α in a pattern similar to that exhibited by type 1 acute-phase proteins in human hepatoma HepG2 cells." (PMID 29513714, 2018). "A cut-off serum-IL-6 level above 100 pg/ml identified 80% of the bile duct cancer patients and excluded healthy adults, all patients with benign bile disease and 92% of the hepatocellular carcinoma patients." (PMID 30038723, 2018). "Moreover, miR-26a suppresses the IL-6-induced growth and metastasis of hepatocellular carcinoma by inhibiting STAT3." (PMID 28388577, 2017). "DUSP22 has been shown to be induced by the pro-inflammatory cytokine interleukin-6 (IL-6) and could dephosphorylate STAT3 in hepatoma cells, creating a feedback loop for the IL-6/STAT3 signaling." (PMID 28902166, 2017). "This isRNA induced IFN-α and to a lesser extent proinflammatory cytokine interleukin-6 (IL-6) production in murine blood serum, efficiently reduced the metastases area in different murine organs and slightly inhibited tumor growth in a hepatocellular carcinoma G-29/CBA/LacSto murine model." (PMID 26981617, 2016). "It is worth mentioning that CUDR plus IL6 may play an important role in the occurrence of hepatocellular carcinoma." (PMID 27833137, 2016). "Previous studies reported that icaritin activates the JNK signaling pathway to promote apoptosis in hepatoma cells, and inhibits the IL-6/Jak2/Stat3 pathway to suppress HCC initiation and malignant growth by inducing the expression of anti-apoptotic factors of the Bcl-2 family." (PMID 27835879, 2016). "In addition, inflammatory cytokines including IL-6 can promote de-differentiation of tumor cells into progenitor cells in hepatocellular carcinoma." (PMID 25767874, 2015). "In consistence with these results, our previous study conducted using germline stem cells, demonstrated that the OCT4 expression was regulated by an IGF-IR-HIF-2α signal loop in pluripotent mouse germline stem cells and a IL-6-IGF-IR signal in HBV-related hepatocellular carcinoma." (PMID 26675296, 2015). "Moreover, studies have revealed that the levels of TNF-α and IL-6 are significantly increased in rats bearing hepatoma, which reflects an aggressive inflammatory response correlated with tumor induction." (PMID 24918094, 2014). "To test whether IL-6 can act directly on the clock in liver cells, we treated liver carcinoma cells (HepG2) with IL-6." (PMID 23527270, 2013). "Furthermore, IL-6 showed prometastatic properties, and an early study demonstrated that exogenously administered IL-6 affected the metastatic potential of rat hepatocellular carcinoma cells." (PMID 23533994, 2013). "Moreover, human hepatoma cells (HuH7) were used to study the effect of IL-6 and TNF-α on HJV mRNA expression." (PMID 22998440, 2012). "An IL-6 dependent TIMP-1 induction was recently demonstrated in a hepatoma cell line." (PMID 21573245, 2011). "To confirm that the hepatoma cells responded to other known stimuli as previously reported and that the cloned hepcidin promoter fragments were functional, we stimulated HepG2 and Huh7 cells with IL-6 and BMP-2." (PMID 19924283, 2009). "Also, interleukin-6 induced CLU expression in hepatoma cells (HepG2) whereas CLU was down-regulated in rat glial cultures exposed to the same cytokine." (PMID 17634137, 2007). "An intriguing recent report showed that IL-6 could counteract the growth inhibitory influence of TGF-β1 in a cultured hepatoma cell line." (PMID 17324269, 2007).
hepatocellular carcinoma (continued). "In human hepatoma HepG2 cell line curdlan sulphate enhances basal and interleukin-6-stimulated fibrinogen and antichymotrypsin (ACT) synthesis, slightly increases basal ceruloplasmin production and exerts only minor effects on alpha-1-proteinase inhibitor and transferrin." (PMID 18472835, 1997). "The resulting HBV-induced ROS accumulation promotes hepatic inflammation through IL-6 upregulation in hepatocellular carcinoma (HCC), concurrently driving constitutive STAT3 activation." (PMID 40918255, 2025). "MO/ascorbic acid–selenium nanoparticles (MO/asc.-Se-NPs) significantly improved antioxidant and anti-inflammatory effects and liver enzyme levels in hepatocellular carcinoma (HCC)-induced Wistar rats, reducing IL-6 and alleviating liver tissue damage." (PMID 40149610, 2025). "MiRNa-let-7b transfer in microvesicles from HCC (hepatocellular carcinoma) cells to macrophages results in the downregulation of IL-6." (PMID 39195233, 2024). "Studies have shown that lipopolysaccharides (LPS) can contribute to hepatocellular carcinoma (HCC) development by inducing IL-6 and TNF-α production from the hepatic progenitor cells." (PMID 38463942, 2024). "In melanoma and hepatocellular carcinoma (HCC), miR-98 suppresses IL-6 and IL-10 expression, respectively, influencing tumor cell migration and invasion, thereby impacting patient survival." (PMID 39731171, 2024). "In the case of human hepatocellular carcinoma (HCC), TAM (tumor-associated macrophage)-derived IL-37 impedes their polarization towards the M2 phenotype by affecting the IL-6/STAT3 axis, eventually inhibiting the growth of the tumor." (PMID 37298214, 2023). "Meanwhile, other studies have reported IL-6/rs2069837 is associated with susceptibility to RA, osteonecrosis of the femoral head (ONFH) and hepatocellular carcinoma (HCC) in Chinese Han population." (PMID 37025289, 2023). "This may be especially important given recent findings observing that dexmedetomidine induced IL-6 secretion from stromal stellate cells and pro-tumorigenic signaling in hepatocellular cancer cells, although whether this is relevant to that distinct TME is to be determined." (PMID 38132444, 2023). "The expression of both IL-6 and IL-6R within the hepatocellular carcinoma (HCC) microenvironment was found to contribute to the recurrence of tumors following surgery." (PMID 37892997, 2023). "Interleukin-6 (IL-6) is a pro-inflammatory cytokine that plays a crucial role in the development and progression of hepatocellular carcinoma (HCC), the most common type of liver cancer." (PMID 37892997, 2023). "Likewise, a study conducted by Yu Li and colleagues proposes that IL-6 could potentially serve as a biomarker indicative of response to sorafenib (PubChem CID:216239) treatment among patients with hepatocellular carcinoma (HCC)." (PMID 37892997, 2023). "For example, human hepatocellular carcinoma (HCC) cells can promote macrophages to secrete IL-6, thus inducing the expansion of HCC stem cells." (PMID 35565418, 2022). "In addition, C5aR1 could promote the expression and secretion of interleukin-6 (IL-6) in hepatoma cells." (PMID 36294966, 2022). "This action is carried out by the suppression of the signaling mediated by the cytokine IL-6 in macrophages and hepatocellular carcinoma cells (HCC), through STAT3 inhibition." (PMID 36004343, 2022). "However, aberrant induction of IL-6 is injurious to the liver and could lead to the development of hepatocellular carcinoma (HCC)." (PMID 34078370, 2021). "Furthermore, analogous results were discovered in mouse H22 hepatocellular carcinoma, with an enhanced anti-tumor immune response; the inhibition of tumor growth; and the suppression of interleukin-6 (IL-6), granulocyte colony-stimulating factor (G-CSF), and keratinocyte-derived chemokine (KC)." (PMID 33816280, 2021).
hepatocellular carcinoma (continued). "As a novel anti-cancer molecule, icaritin has been shown to suppress hepatocellular carcinoma (HCC) initiation and malignant growth through the Interleukin-6/Janus-activated kinases 2/Signal transducer and activator of transcription 3 pathway." (PMID 34068926, 2021). "IL-6 is known to induce hepatic inflammatory cell infiltration, while PNPLA3 represents a modifier of progression of hepatocellular injury and liver-associated disorders such as steatohepatitis, chronic hepatitis, and hepatocellular carcinoma by promoting the release of inflammatory cytokines." (PMID 33808318, 2021). "This is particularly shown in hepatocellular carcinoma (HCC) whereby, the increased hepatic mRNA levels of FNDC5/irisin in HCC patients correlated with increased expression of proinflammatory markers, such as IL-6 and TNF-α." (PMID 33614663, 2021). "Expression of lncRNA TSLNC8 was reduced in hepatocellular carcinoma (HCC) tissues and altered interleukin-6/STAT3-associated genes/pathways, cell proliferation and metastasis in HCC." (PMID 37304650, 2021). "Interestingly, IL-6 enhances C3 transcription and secretion in a rat hepatoma cell line." (PMID 32244854, 2020). "IL-6 has also been related to hepatocellular carcinoma (HCC), the most common liver cancer, mainly in males, both in humans and in mice, probably due to the inhibitory effects of oestrogens on IL-6 production in females." (PMID 32824349, 2020). "In a co-culture of hepatocellular carcinoma (HCC) cells and macrophages, IL-6/STAT3 signaling pathway was suppressed in M1 macrophages but was activated in M2 macrophages." (PMID 32486098, 2020). "Also, IL6 produced by TAMs promotes CSCs expansion in hepatocellular carcinoma." (PMID 33224886, 2020). "In addition to the regulation of cancer progression, such as ovarian cancer cells, TAM-secreted IL-6 is also reported to increase the expansion of CD44+ stem cells as well as sphere formation of the hepatocellular carcinoma cells, thus promoting tumor progression through cancer stem cell growth." (PMID 32283687, 2020). "This study provides in vitro and in vivo evidences that HSCs induce the generation of MDSCs to promote hepatocellular carcinoma (HCC) progression through interleukin (IL)-6 secretion." (PMID 31614930, 2019). "Persistent activation of IL-6 trans-signalling on damaged hepatocytes can ultimately lead to the development of hepatocellular carcinoma (HCC)." (PMID 31601007, 2019). "Ncoa5+/− male mice developed glucose intolerance, hepatic steatosis and hepatocellular carcinoma (HCC), which can be partially reversed by heterozygous deletion of Il-6 gene." (PMID 31664153, 2019). "In hepatocellular carcinoma (HCC), tumor-associated macrophages promote CD44+ stem-like cell expansion, and IL-6/STAT3 signaling inhibition using Tocilizumab (TCZ) inhibits this expansion." (PMID 30804456, 2019). "Tim3 expression on TAMs also correlates negatively with HCC patient survival, most likely via the promotion of pro-inflammatory IL-6 production by Tim3 expressing macrophages, which is thought to be essential for the development of hepatocellular carcinoma." (PMID 31798592, 2019). "A recent study has suggested that arecoline can reduce IL-6 and STAT3 in a human hepatoma cell line at concentrations of 0, 3, 30 and 100 μg/ml: in contrast, we found that arecoline treatment at 0.025 μg/ml could upregulate IL-6 and STAT3 mRNA expression in ORL-48(T) cells." (PMID 29385191, 2018). "In addition, HBx induced IL-6 production in hepatocytes and hepatoma cells, IL-6 could trigger hepatic cells proliferation and liver regeneration, and modulate synthesis of collagen I42." (PMID 27883059, 2016). "Interleukin-10 (IL-10) and interleukin-6 (IL-6) have been reported to be related to hepatocellular carcinoma (HCC) prognosis." (PMID 27335826, 2013).